CX3CR1 (C-X3-C motif chemokine receptor 1)
Diseases named in the same sentence as CX3CR1 in open-access papers (continued):
Sharing a sentence is not in itself a finding about the gene and the disease.
Hypertension (11 papers, 2017 to 2025). The presence of chronic increased pressure in the systemic arterial system. "Studies have shown that hypertension- and unilateral ureteral obstruction-induced renal fibrosis are attenuated by Cx3cr1 gene deficiency." (PMID 29203799, 2017). "Recently, CX3CR1 has been identified as a potential therapeutic target for hypertension and diseases related to autonomic nerve function." (PMID 38271077, 2024). "Recent evidence suggests that CX3CR1 is associated with inflammatory response in the brain of hypertensive animal models, and inhibition of CX3CR1 microglia signaling attenuates hypertension and chronic brain inflammation." (PMID 35326484, 2022). "ICV administration of AZD8797, a CX3CR1 inhibitor, attenuates fructose-induced hypertension and expression of pro-inflammatory cytokines IL-1β, IL-6, and TNF-α." (PMID 32532282, 2020). "The hypertensive rat model was used to study the role of CX3CR1-microglia in NTS inflammation following hypertension induction by oral administration of 10% fructose water." (PMID 32532282, 2020). "We conclude that CX3CR1-microglia represses the nNOS signaling pathway and promotes chronic inflammation in fructose-induced hypertension." (PMID 32532282, 2020). "For this reason, we selected AZD8797 to inhibit CX3CR1 for investigating its pharmacological role towards inflammation during hypertension." (PMID 32532282, 2020). "Inhibited CX3CR1-microglia signaling attenuates fructose-induced hypertension and chronic brain inflammation." (PMID 32532282, 2020). "In this study, we report that CX3CR1-microglia in the NTS plays a role in fructose-induced hypertension." (PMID 32532282, 2020). "In summary, we showed that AZD8797, a CX3CR1 inhibitor, attenuated fructose-induced hypertension and expression of pro-inflammatory cytokines, IL-1β, IL-6, and TNF-α." (PMID 32532282, 2020). "Therefore, it is essential to investigate the role of FKN and its receptor CX3CR1 after hypertension induced by fructose." (PMID 32532282, 2020). "Our novel findings suggest that CX3CR1-microglia may be a potential candidate for treating hypertension and relieving autonomic nerve function through reestablishment of normal crosstalk between the neuron and microglia." (PMID 32532282, 2020). "Further investigation of the molecular mechanisms involving blood pressure regulation may unravel the pathogenesis of CX3CR1-microglia and brain inflammation in hypertension." (PMID 32532282, 2020). "Finally, microglia activation in the NTS requires CX3CR1 to promote fructose-induced hypertension progression." (PMID 32532282, 2020). "Our previous studies found that C-X3-C motif chemokine receptor 1 (CX3CR1) functions as a microglia biomarker, and that microglia suppresses the nNOS signaling pathway and promotes chronic inflammation in fructose-induced hypertension." (PMID 34829655, 2021). "Similarly, in a mouse model of hypertension, the combination of deoxycorticosterone and high salt diet following unilateral nephrectomy resulted in elevated mRNA for both CX3CL1 and CX3CR1 within the kidneys." (PMID 34163473, 2021).
multiple myeloma (11 papers, 2015 to 2025). "The CX3CL1/CX3CR1 axis has been previously implicated in the interaction between multiple myeloma cells and the bone microenvironment, and also associated with cell survival and disease progression." (PMID 32211606, 2020). "CX3CR1 is expressed in some multiple myeloma (MM) cell lines, where stimulation with CX3CL1 has been shown to activate Akt and ERK1/2 signaling pathways and enhance cell adhesion." (PMID 40508161, 2025). "In multiple myeloma (MM), CX3CR1 contributes to tumor progression, osteoclast activation, and angiogenesis." (PMID 40508161, 2025). "The expression of CX3CR1 (also known as fractalkine) has recently been detected in human myeloma cell lines and is reported to induce osteoclast differentiation." (PMID 32211606, 2020). "In particular, the CX3CL1/CX3CR1 axis supports cooperation between multiple myeloma and osteoclast cells to promote adhesion of MM cells to bone extra cellular matrix (ECM), which is a required process for disease progression." (PMID 32211606, 2020). "This study proves the crucial role of fractalkine in bone tumors, consistent with the previous finding that the fractalkine/CX3CR1 axis plays a crucial role in the bone microenvironment of multiple myeloma metastasis." (PMID 28903329, 2017). "Additionally, the activation of CX3CR1 on human myeloma RPMI-8226 cells increases their adhesion to fibronectin and vascular cell adhesion molecule-1 (VCAM-1), which is associated with the migration of these cells to bone marrow." (PMID 32466280, 2020). "The role of the CX3CL1/ C-X3-C motif chemokine receptor 1(CX3CR1) axis in the multiple myeloma (MM) microenvironment is still unknown." (PMID 30845779, 2019). "In multiple myeloma, fractalkine induces Akt activation and cell adhesion through CX3CR1." (PMID 28903329, 2017). "In other hematological cancers, CX3CR1 and its ligand, CX3CL1, have been proposed to be involved in the interaction between chronic lymphocytic leukemia cells and their microenvironment, and CCR1 has a crucial role in the pathogenesis of myeloma-associated bone disease." (PMID 27258612, 2016). "We found that there was significant correlation between the proportion of CX3CR1+, CD16+CD14dim non classical monocytes, and percent plasma cells (PC) in the bone marrow of myeloma patients." (PMID 26029369, 2015).
osteoarthritis (11 papers, 2014 to 2025). A noninflammatory degenerative joint disease occurring chiefly in older persons, characterized by degeneration of the articular cartilage, hypertrophy of bone at the margins and changes in the synovial membrane. "Within the pathologies of the musculoskeletal system, the role of the CX3CL1/CX3CR1 axis was to date associated with development of conditions that include, but are not limited to, osteoarthritis (OA), rheumatoid arthritis (OA), and degenerative disc disease (DDD)." (PMID 32884948, 2020). "Genes associated with DDH and osteoarthritis include FRZB, CX3CR1, ASPN, DKK1, PDRG1, GDF5, UQCC1, and TGF-β1." (PMID 41019141, 2025). "Previous studies have demonstrated that the CX3CL1/CX3CR1 axis is involved in cartilage destruction due to osteoarthritis by inducing MMP-3 secretion from synovial fibroblasts through c-Raf, MEK, ERK, and NF-κB pathways." (PMID 38283363, 2023). "This study is the first to systematically construct a miRNA–mRNA regulatory network centered on CX3CR1 and CEBPB, identifying several miRNAs previously unreported in the context of osteoarthritis (OA)." (PMID 41007174, 2025). "Previous studies proved overexpression of CX3CR1, the receptor for FKN, is closely related to the pathogenesis of osteoarthrosis by regulation of chondrocyte proliferation and apoptosis via the Wnt/β-catenin pathway." (PMID 30919150, 2019).
renal fibrosis (11 papers, 2017 to 2025). A final common manifestation of a wide variety of chronic kidney diseases characterized by glomerulosclerosis and tubulointerstitial fibrosis. "In this study, renal fibrosis following UUO was increased in CX3CR1-deficient mice compared to their wild type counterparts." (PMID 34163473, 2021). "has raised questions about the role of CX3CR1-CX3CL1 signalling in promoting renal fibrosis, instead providing experimental evidence that CX3CR1 deficiency can result in accelerated renal fibrosis under some circumstances." (PMID 34163473, 2021). "Renal fibrosis was induced in wild-type diabetic mice but was attenuated in CX3CR1-deficient animals." (PMID 34163473, 2021). "Similar to other reported models, renal fibrosis was attenuated in CX3CR1-deficient mice after UUO." (PMID 34163473, 2021). "The role of CX3CR1 in renal fibrosis is a matter of controversy." (PMID 40046045, 2025). "Thus, CX3CR1 is expressed on dendritic cells and macrophages of specific subset and is involved in renal fibrosis." (PMID 40508161, 2025). "For example, intravitreal injection of anti‐mouse FKN antibody could reduce the retinal angiogenesis in the oxygen‐induced retinopathy model, and CX3CR1 depletion could attenuate renal inflammation, renal fibrosis and renal injury in diabetic nephropathy model." (PMID 35023309, 2022). "Therefore, it is debatable whether the CX3CL1/CX3CR1 axis contributes to renal fibrosis." (PMID 40508161, 2025). "Furthermore, human cortical fibroblast cell lines also express CX3CR1 and migrate towards the CX3CL1 in dose-dependent manner, suggesting a functional role for CX3CL1/CX3CR1 in promoting renal fibrosis through fibroblast recruitment." (PMID 40508161, 2025). "Additionally, increased mRNA expression for CX3CR1 has been detected during early stages of DN.CX3CR1 knock out can improve kidney damage in streptozotocin-induced diabetic mice, reducing ECM deposition and macrophage infiltration, thereby alleviating renal fibrosis and inflammation." (PMID 38951833, 2024).
epilepsy (10 papers, 2016 to 2025). A brain disorder characterized by episodes of abnormally increased neuronal discharge resulting in transient episodes of sensory or motor neurological dysfunction, or psychic dysfunction. "Regarding the effects of the FKN/CX3CR1 axis on the hyperexcitability and neurodegeneration associated with epilepsy, FKN is increased in the pilocarpine-induced status epilepticus (SE) rat model, contributing to microglial activation, hyperexcitability, and neurodegeneration." (PMID 36644710, 2023). "FKN and CX3CR1 levels are increased in epilepsy patients and rodent epilepsy models; although, the persistence of such changes in animal models remains controversial." (PMID 36644710, 2023). "Our results indicated that epilepsy facilitated migraine through FKN/CX3CR1 axis-mediated microglial activation in the cortex/thalamus/sp5c, which was accompanied by BDNF release." (PMID 35382731, 2022). "Blocking the FKN/CX3CR1 axis and microglial activation are potential therapeutic strategies for preventing and treating migraine in patients with epilepsy." (PMID 35382731, 2022). "The reduction in microglial cells and the decreased number of degenerated neurons was also described after infusion of a CX3CR1 antibody into the pilocarpine-induced model of epilepsy." (PMID 33065974, 2020). "In the context of epilepsy, microglia and astrocyte activation is routinely observed in the epileptic brain foci from patients, alongside elevated levels of CX3CR1, IL-6 and TNF-α." (PMID 31717556, 2019). "Similarly, seizure severity in an epilepsy model induced by kainic acid is exacerbated in CX3CR1−/− mice compared to wild-type animals." (PMID 36644710, 2023). "Our research aimed to investigate whether microglia and their interactions with neurons via the FKN/CX3CR1 axis in the thalamic cortical network are involved in the comorbidities of epilepsy and migraine by regulating the expression of BDNF." (PMID 35382731, 2022). "To determine whether the FKN/CX3CR1 axis is involved in the pathological mechanism of migraine after epilepsy, we measured the protein levels of FKN and CX3CR1 in the temporal cortex, thalamus, and sp5c of SE model rats four days after seizures." (PMID 35382731, 2022). "However, only a few studies have shown the role of fractalkine/CX3CR1 axis signaling in the pathogenesis of epilepsy and the accompanying cell death." (PMID 33065974, 2020). "In rodent epilepsy models, seizure activity induces upregulation of the FKN/CX3CR1 axis and microglial activation; pharmacological inhibition of CX3CR1 attenuates microglial activation and neurodegeneration." (PMID 41007696, 2025). "Nevertheless, immune cell entry occurs in the epileptogenic focus in drug-resistant epilepsy, and the peripherally-detected FLAG-Ago2 from the Cx3cr1 mouse line containing miRNA may have originated from centrally-driven pathophysiologic actions of these cells." (PMID 37808470, 2023). "Although epilepsy is not considered a primary immune-mediated disease, DRE microglial clusters 7, 5, 9 and 11 were characterized by high gene expression levels of TNF, HLA-DRA and HLA-DPB1 and low CX3CR1 and P2RY12 gene expression levels." (PMID 35739273, 2022).
neuroblastoma (10 papers, 2016 to 2022). Neuroblastoma (NB) is the most common solid, extracranial childhood tumor. "It has been shown that TGF-β1 released by neuroblastoma tumor cells down-regulated the surface expression of CX3CR1 in human NK cells." (PMID 32161594, 2020). "In this context, a low expression of CX3CR1 has been reported in CD56dim NK cells in both peripheral blood and tumor-infiltrated bone marrow (BM) of neuroblastoma patients." (PMID 30641867, 2019). "Other studies have shown similar reductions in chemokine receptor expression in the presence of TGF-β: CX3CR1 levels decreased in NK cells when exposed to neuroblastoma-derived TGF-β." (PMID 31547819, 2019). "In this case, the outcome of the overall chemokine receptor modulation is less clear-cut; however, the downregulation of CX3CR1 suggests that the recruitment of cytotoxic CD56dim NK cells may be reduced in neuroblastoma lesions." (PMID 32272610, 2020). "Interestingly, in agreement with this ability of tumors in inducing a regulatory milieu, an unusual low expression of CX3CR1 has been reported in CD56dim NK cell population of tumor-infiltrated bone marrow and peripheral blood of Neuroblastoma (NB) patients." (PMID 30364222, 2018). "Moreover, in neuroblastoma, the fractalkine/CX3CR1 axis promotes transendothelial migration and contributes to bone marrow metastasis through Akt activation." (PMID 28903329, 2017). "Finally, we showed that neuroblastoma cells induced in resting NK cells a downregulation of the CX3CR1 expression that was paralleled by a significant increase of miR-27a-5p expression." (PMID 28791023, 2017). "TGF-β1 produced by neuroblastoma cell lines was shown to upregulate the surface expression of CXCR4 and CXCR3 on both CD56high and CD56low NK cells, while it downregulated CX3CR1 in the CD56low subset." (PMID 27766097, 2016). "Finally, neuroblastoma cells have been shown to upregulate CXCR4 and CXCR3 and reduce CX3CR1 expression on NK cells via the release of TGF-β." (PMID 32272610, 2020). "Similarly, neuroblastoma cells have been shown to upregulate CXCR4 and CXCR3 on both CD56dim and CD56bright NK cells and to reduce CX3CR1 (which is important for NK cell extravasation) on CD56dim NK cells viarelease of TGF-β." (PMID 32272610, 2020). "Similar results were observed for AktSer473phosphorylation at time points 10, 20 and 40 min upon chemokine stimulation.A similar time course of kinase phosphorylation by CX3CL1 was described formonocytic cells, CX3CR1-transfected HEK293T cells, neuroblastoma and osteoarthritisfibroblasts." (PMID 28739588, 2017).
glaucoma (9 papers, 2016 to 2024). Increased pressure in the eyeball due to obstruction of the outflow of aqueous humor. "The chemokine receptor CX3CR1 regulates microglial neurotoxicity in an experimental mouse glaucoma model; CX3CR1 deficiency increased microglial neurotoxicity and subsequently induced more extensive RGC loss than control mice with CX3CR1." (PMID 31355256, 2019). "Our findings suggest that distinct mechanisms may contribute to different aspects of RGC decline in glaucoma, with axonal transport selectively altered after loss of Cx3cr1 in microglia and/or macrophages." (PMID 27932942, 2016). "Our findings suggest that distinct mechanisms may contribute to different aspects of RGC decline in glaucoma, with axonal transport selectively altered after loss of Cx3cr1 in myeloid cells such as microglia and macrophages." (PMID 27932942, 2016). "Meanwhile, a deficiency in C-X3-C motif chemokine receptor 1 (CX3CR1), which is expressed by neurons, can inhibit microglial reactivity, aggravate neurotoxicity, and induce extensive damage to RGCs in an experimental mouse glaucoma model with transient elevation of IOP." (PMID 34121982, 2021). "Conversely, genetic deletion of the microglial homeostatic checkpoint, Cx3cr1, exacerbated both RGC loss and axonal transport dysfunction in glaucoma models, perhaps by decreasing the threshold for microglial activation." (PMID 36779012, 2023). "Microglia express the chemokine fractalkine receptor (CX3CR1), and their signaling could regulate microglial behavior in glaucoma." (PMID 33669765, 2021). "In addition, a deficiency in CX3CR1, which is expressed in the microglia, has been shown to increase microglial activation, inducing RGC loss, in an experimental mouse glaucoma model." (PMID 31443568, 2019). "In the context of data from a model of glaucoma in which an anti-inflammatory agent, crocin, successfully reduced microglial activation via CX3CR1 upregulation, this might indicate an anti-inflammatory effect in MSA." (PMID 29850876, 2018). "Furthermore, if neuron-microglia communication is impaired by interfering with the fractalkine receptor (CX3C chemokine receptor 1, Cx3cr1) in microglia, this would aggravate RGC loss in disease models such the ischemia-reperfusion and glaucoma DBA/2J mouse, with no alterations in uninjured retinas." (PMID 32218163, 2020).
Hyperglycemia (9 papers, 2015 to 2026). An increased concentration of glucose in the blood. "Pseudotime trajectory analysis indicates a gradual downregulation of Trem2, CCR5, and Cx3cr1, suggesting that chronic hyperglycemia induces functional exhaustion of microglia." (PMID 41484634, 2026). "Alternatively, other studies also demonstrated that hyperglycemia induced upregulation of the C-X3-C motif chemokine ligand 1 (CX3CL1)/C-X3-C motif chemokine receptor 1 (CX3CR1) signaling pathway, which is known to disturb placental perfusion." (PMID 34489862, 2021). "Furthermore, knockdown of CX3CR1 (fractalkine receptor) in a mouse model was found to induce hyperglycaemia and to reduce nutrient-stimulated insulin secretion." (PMID 35185804, 2022). "The regulatory impact of ERV1 on CCR2 and CX3CR1 in monocytes favored patrolling over inflammatory phenotype in both steady state and during dietary fat overload conditions, with a net positive metabolic impact reflected by prevention of hyperglycemia." (PMID 28993702, 2017). "Immunohistochemical analysis of retinal tissues after four months of hyperglycemia revealed a decrease in NeuN+ neuronal densities in diabetic CX3CR1-WT and hCX3CR1I249/M280 mice in comparison to the non-diabetic CX3CR1-WT (3646 ± 811.7) control group." (PMID 37033925, 2023). "An increase in CX3CR1 protein content in placental lysates was observed in the NG subgroups B and C. Also, resveratrol significantly decreased NF-κBp65 protein content only in the NG group, not affecting hyperglycemia-elicited TNFR1 upregulation." (PMID 28655972, 2017).